IL24 (interleukin 24)
Diseases named in the same sentence as IL24 in open-access papers (continued):
Sharing a sentence is not in itself a finding about the gene and the disease.
infection (continued). "Depending on the multiplicity of infection, it can be speculated that IL-24 is largely over-expressed from within the cell by such a regimen and this is likely to induce ER stress responses, which culminate in cell death." (PMID 18074024, 2007). "Indeed, anti-inflammatory genes exhibited a considerable presence in the infection setting; the IL-10 family of genes important for wound healing and repair (IL1r2, IL1r1, IL-24, IL-19, IL-22) were elevated >2- to 60-fold, although IL-10 itself remained unchanged." (PMID 40586608, 2025). "IL‐24 induced neutrophils to produce IFN‐γ, NO, and IL‐12, leading to activation of CD8+ T cells and a robust host response to combat infection." (PMID 40338095, 2025). "The modulation of IL-24 by IL-4 and IFN-g in their study provides a critical link to the cytokine-driven dynamics we observed in our transcriptional profiles post-infection." (PMID 39591472, 2024). "If this IL-24-mediated tissue injury response is analogous to pathogen infection where IFNs are upstream of STAT1/2, then IL-24 should be important for STAT3 activation in wounds." (PMID 37098344, 2023). "The combination of both TMAO and CFT073 had significant additive effects on the release of IL-18R1 and synergistic effects on the release of IL-6, IL-24, IL-33, LIF, TGF-α, and LAP TGF-β1 compared to CFT073 infection alone." (PMID 37111409, 2023). "A more detailed analysis of DEGs indicated on a strong immune response in MKN-28 cells after 2-h infection based on increased transcription of IL1A, IL8, IL24, CXCL2, CXCL3 and CCL20." (PMID 37193047, 2022). "In addition, IL-24, a Th2-associated cytokine was significantly upregulated in B.1.1.7 compared to VIDO-01 that may coincide with the significant influx of B cells into the lung organoid during B.1.1.7 infection." (PMID 36298826, 2022). "Under these experimental conditions, Ad.5-E1A expressed only the Ad5 E1A protein, whereas Ad.5-CTV and Ad.5-TCTV infection resulted in comparable levels of expression of Ad5 E1A (protein) and MDA-7/IL-24 (mRNA and protein)." (PMID 33670594, 2021). "Consistent with previous reports showing that MDA-7/IL-24 inhibits angiogenesis, induces apoptosis by inhibiting Bcl-2, and promotes ER stress, Ad.5-TCTV infection reduced CD-31 and Bcl-2 levels and increased GRP-78 protein levels in treated tumors." (PMID 33670594, 2021). "DUSP1, IL-24, and DUSP6 were induced 2–3 hours post-infection with the high dose of wild-type C. albicans and reached a maximal level of induction ~6 hours post-infection." (PMID 27088599, 2016). "To evaluate oncolytic potency of armed CRAd-IL24 and CRAd-ING4 with respect to control CRAd we carried out multiple assays measuring cell viability following infection at a wide range of MOIs." (PMID 27349517, 2016). "While CRAd-IL24 and CRAd-ING4 infection resulted in somewhat similar cytotoxicity increase in SKO3luc cells as compared to control CRAd we did not observe any significant differences between CRAd vectors in OV-4 and IOSE-120/523 cells." (PMID 27349517, 2016). "Similar to MDC staining, after infection, GFP-LC3 staining increased in AdLTR2EF1α-IL-24 treated KB cells, when compared with the AdLTR2EF1α-vec treated groups." (PMID 26361755, 2015). "Here we compared the efficacy ofthe IFN-α treatment, or intratumoral infection oncolytic adenovirus thatexpressed IL-24, SG600-IL-24 or both to a PBS control in a HCC xenograft in a nudemouse model." (PMID 22569271, 2012). "Finally, elimination of infection resulted in significantly decreased frequencies of antigen – specific CD4+ T cells expressing IL-10, IL-19 and IL-24." (PMID 24699268, 2014). "The number of regulated genes declined at 48 h post infection to 5.4% and increased again in the chronically infected cells to constitute 10.1% of the genes in this category, with a modified spectrum of highly induced genes, namely IL3RA, IL6, IL24 and SPRY4." (PMID 23326599, 2013).
infection (continued). "Treatment of filarial infection and consequent cure resulted in significantly decreased frequencies of CD4+ T cells expressing IL-10, IL-19, IL-24 and IL-26 after parasite-antigen stimulation whereas those who continued to harbor infection did not exhibit reduction in these frequencies." (PMID 24699268, 2014). "Finally, we tested if supplementing infection media with Avastin (Bevacizumab), a recombinant humanised monoclonal antibody developed against soluble VEGF to prevent receptor binding, may increase oncolytic potency of CRAd-IL24 and/or CRAd-ING4 in OvCa cells." (PMID 27349517, 2016). "Interestingly, IL-20 has been previously shown to play a rather negative role in host defense; infection with Staphylococcus aureus led to the early up regulation of IL-20 family members (IL-19, IL-20 and IL-24), inhibiting the local generation of IL-1β and IL-17A." (PMID 26023727, 2015). "Additionally, quantitative realtime PCR was performed to validate RNA-seq data and the transcript levels of cytokines/chemokines, such as CXCL10, CXCL11, IFN-γ, TNF-α and IL-24, were all up-regulated upon H5N1 and H5N8 infection (data not shown)." (PMID 26576844, 2015).
cardiovascular disease (5 papers, 2016 to 2025). "Based on the current literature, it seems that IL-24 has a diverse role in cardiovascular disease." (PMID 27271601, 2016). "In spontaneously hypertensive rats, 16 differentially regulated genes were identified including IL-24, which were previously not implicated in cardiovascular disease." (PMID 27271601, 2016).
bacterial infection (3 papers, 2016 to 2022). "To begin to assess whether cells within the CNS can express IL-24, we have determined whether mRNA encoding IL-24 is present in the CNS either constitutively or following bacterial infection." (PMID 30825881, 2019). "This gives IL-24 a dual-role in host defense, where it can be both protective and antagonistic depending on the type of bacterial infection." (PMID 27271601, 2016). "IL-24 also plays a role in host defense during bacterial infections." (PMID 27271601, 2016).
immune diseases (3 papers, 2018 to 2025). "This aligns with previous studies highlighting the influence of IL24 on sex differences in immune diseases." (PMID 38792924, 2024). "Moreover, IL24’s connection to sex-specific differences in immune diseases underscores the need to scrutinize its involvement in the sexual dimorphism observed in OA." (PMID 38792924, 2024). "Furthermore, several key genes (e.g., Csf1r, Ifnb1, IL-20, IL-22, IL-24, Jhdm1d, Csf1r, Ifnb1, IL-20, IL-22, IL-24, and Tgfb2 that regulate sex differences in immune diseases) were discovered." (PMID 30246031, 2018). "Interestingly, IL-24 is a common and specific autoantigen of IgE in patients with chronic spontaneous urticarial, highlighting a potentially broad implication of IL-24 in immune disorders." (PMID 38752989, 2025).
infectious disease (3 papers, 2016 to 2022). A disorder directly resulting from the presence and activity of a microbial, viral, or parasitic agent in humans. "We and others have previously reported that IL-24 inhibits the production of proinflammatory cytokines from Th1 and Th17 cells in cases of inflammatory and infectious disease." (PMID 36233291, 2022). "Controversy remains as to the regulatory activity of IL-24 to immune systems in infectious diseases." (PMID 31921658, 2019).
kidney disease (3 papers, 2020 to 2025). "Cytokines Il19 and Il24, implicated in epithelial injury and fibrosis in human kidney disease and in mouse models, were almost undetectable in control and strongly expressed in diseased kidney." (PMID 40533345, 2025). "Our data confirmed the significance of IL-19, IL-20 and IL-24 in the pathomechanism of renal diseases." (PMID 32306980, 2020). "We examined the renal presence of IL-19, IL-20, and IL-24, and their receptors in animal models of different kidney diseases and in renal biopsies of patients with different renal diseases." (PMID 32306980, 2020). "The expression of Il19, Il20 and Il24 increased in the animal models of various kidney diseases." (PMID 32306980, 2020). "Recently, the role of IL-19, IL-20 and IL-24 has been reported in renal disorders." (PMID 32306980, 2020). "However, the effect of IL-24 in kidney disease needs to be identified in the future." (PMID 32028746, 2020). "Renal Il19, Il20 and Il24 expression was determined in ischemia/reperfusion, lipopolysaccharide, streptozotocin, or UUO induced animal models of kidney diseases." (PMID 32306980, 2020).
head and neck tumor (2 papers, 2021 to 2022). "Also, its imaging performance was tested in vitro (phantom) and in vivo, in Balb/c nude mice bearing a head and neck tumor xenograft treated with novel gene therapy [a new approach to the delivery of recombinant bacterial gene (IL-24-expressing strain)]." (PMID 35814447, 2022).
inflammation (2 papers, 2024 to 2025). Aberrant reaction of the microcirculation characterized by movement of fluid and leukocytes from the blood into extravascular tissues. "IL-24 and IL-19 are key factors in IBD-related intestinal inflammation and this is one of the few human studies to suggest that." (PMID 39007024, 2024). "In non-immune contexts, IL-24 contributes to epithelial inflammation in the skin, modulates fibrogenic activity in pancreatic myofibroblasts, and exerts cytoprotective effects in endothelial cells under oxidative stress conditions." (PMID 40607413, 2025).
brain disorder (1 paper, 2018). A disease affecting the brain or part of the brain. "While it is clear that glia can be a significant source of IL-10, IL-19 and perhaps IL-20 and IL-24, and these resident CNS cells are responsive to their actions, the functions of the IL-10 cytokine family in health and brain disorders have been understudied." (PMID 30542269, 2018).
intestinal disease (1 paper, 2023). "Some studies reported changes of IL-24 in intestinal disease, and no studies have investigated the relationship between IL-24 and the occurrence of NEC." (PMID 36806964, 2023).
IL24 also shares sentences with these, for which no sentence is quoted: bladder cancer (3 papers); chronic spontaneous urticaria (3); nasopharyngeal carcinoma (3); neuroblastoma (3); skin inflammation (3); Crohn disease (2); triple-negative breast carcinoma (2); abdominal aortic aneurysm (1); acute myeloid leukemia (1); adenocarcinoma (1); adenovirus infection (1); adrenal carcinoma (1); brain tumors (1); bullous pemphigoid (1); B‐cell acute lymphoblastic leukaemia (1); colorectal tumor (1); contact dermatitis (1); cutaneous squamous cell carcinoma (1); cyst (1); dermatitis (1); eosinophilic esophagitis (1); experimental autoimmune encephalomyelitis (1); gastrointestinal disease (1); gastrointestinal infections (1); hematological malignancies (1); infectious colitis (1); Insulin resistance (1); keratitis (1); Kidney Damage (1); large cell lymphoma (1).
A further 22 diseases each share a sentence with IL24 in 1 paper.